GPX1 (glutathione peroxidase 1)
Diseases named in the same sentence as GPX1 in open-access papers (continued):
Sharing a sentence is not in itself a finding about the gene and the disease.
Stroke (7 papers, 2020 to 2024). Sudden impairment of blood flow to a part of the brain due to occlusion or rupture of an artery to the brain. "The stroke susceptibility of GPx1-deficient mice was explored using the middle cerebral artery-ischemia reperfusion model (MCA I/R)." (PMID 34579115, 2021). "In addition, the knockdown of GPX1 in PT mice caused significant increases in the volume of the brain infarct after stroke." (PMID 37673878, 2023). "Moreover, pre-activation of the apoptosis marker, caspase 3, was reported in the stroke model, suggesting that the neuronal protective activity against the oxidative state and Gpx-1 deficiency may initiate the neuronal apoptosis program." (PMID 36875474, 2023). "This study explored the role of allicin in stroke and demonstrated that the administration of allicin improved behavior recovery after stroke and enhanced neuroplasticity by regulating GPX1." (PMID 37673878, 2023). "The lentiviral vector shRNA-GPX1 and its control shRNA-Con were used to further demonstrate the effect of GPX1 on stroke recovery." (PMID 37673878, 2023). "Mice in the PT group with allicin stimulation were used to explore the potential mechanism of action of GPX1 in stroke." (PMID 37673878, 2023). "Therefore, GPX1 plays a vital role in post-stroke functional impairment, and allicin may improve this impairment by increasing GPX1 expression." (PMID 37673878, 2023). "After stroke, dBET1 dramatically reduced oxidative damage levels revealed by decreased 4-HNE, a lipid peroxidation product, and gp91phox, a major source of oxygen radical generation, and improved the expression levels of antioxidant enzymes SOD2 and GPx1." (PMID 35761277, 2022). "dBET1 markedly reduced inflammation and oxidative stress after stroke, indicated by multiple pro-inflammatory cytokines and chemokines including IL-1β, IL-6, TNF-α, CCL2, CXCL1 and CXCL10, and oxidative damage markers 4-hydroxynonenal (4-HNE) and gp91phox and antioxidative proteins SOD2 and GPx1." (PMID 35761277, 2022).
autism (6 papers, 2011 to 2024). Persistent deficits in social interaction and communication and interaction as well as a markedly restricted repertoire of activity and interest as well as repetitive patterns of behavior. "Polymorphisms in glutathione S-transferase mu 1 (GSTM1), glutathione S-transferase pi 1 (GSTP1), and glutathione peroxidase 1 (GPX1), which modulate the response to oxidative stress, have been associated with increased autism risk." (PMID 21156395, 2011). "However, given the multifactorial nature of autism, this evidence might be a piece of a more complex puzzle being the GPx1 enzyme part of a complex pathway in which several proteins are involved." (PMID 34997988, 2022). "GPX1, a gene that acts against oxidative stress, also exhibited decreased expression in the astrocytes of patients with autism (~40%, p = 0.015) but not quite a significant decrease in neurons (~30%, p = 0.05, one-tailed t-test) or in NSCs." (PMID 38994948, 2024). "Moreover, the astrocytes of patients with autism exhibited higher expression of TGFB1 and TGFB2 but reduced expression of proliferator genes such as CXCR4 and NURR1 in addition to RELN, EN2, HAP1, SIRT1, and GPX1 vs. controls." (PMID 38994948, 2024).
leukemia (6 papers, 2016 to 2025). A malignant (clonal) hematologic disorder, involving hematopoietic stem cells and characterized by the presence of primitive or atypical myeloid or lymphoid cells in the bone marrow and the blood. "During the past two decades, GPX1 Pro198Leu polymorphism has been extensively studied in various cancer types, mainly breast, bladder, prostate, lung, leukemia, and colon cancers." (PMID 35626163, 2022). "In leukemia, high GPX1 expression is associated with a poor prognosis of AML patients." (PMID 40346054, 2025). "GPX1 is overexpressed in thyroid cancer, glioma and skin melanoma, as well as leukemia." (PMID 40346054, 2025).
non-small cell lung carcinoma (6 papers, 2013 to 2022). A group of at least three distinct histological types of lung cancer, including non-small cell squamous cell carcinoma, adenocarcinoma, and large cell carcinoma. "GPX1 expression is upregulated in non-small cell lung cancer (NSCLC) cell lines resistant to cisplatin." (PMID 35626163, 2022). "It has been reported that overexpression of metallothionein confers resistance to anti-cancer drugs; GPX1 promotes cisplatin resistance via ROS-Induced activation of PI3K/AKT pathway in non-small cell lung cancer." (PMID 34395436, 2021). "GPX1 was found to be significantly increased and survivin was reduced following resveratrol treatment in non-small-cell lung carcinoma cells, which suggested that GPX1 might be involved in the inhibition of tumor cell proliferation." (PMID 24228025, 2013). "As the peptide-Au clusters could well suppressing the GPx-1 activity in buffer solution, we further check if the peptide-Au clusters could be taken into human non-small cell lung carcinoma cells (A549 cells), suppress the GPx-1 and further up-regulate the ROS level in cell." (PMID 28273930, 2017).
renal cell carcinoma (6 papers, 2019 to 2024). "High GPX1 level in patients with renal cell carcinoma (RCC) is positively associated with poor OS, distant metastasis, lymph node metastasis, and tumor stage." (PMID 35626163, 2022). "Similar results have been obtained in patients with renal cell carcinoma (RCC), where high expression of Gpx-1 is positively associated with distant metastases, lymph node metastases, and tumour stage." (PMID 37242524, 2023). "In summary, we confirm the high expression of GPX1 promoted the progression in renal cell carcinoma." (PMID 31844035, 2019). "Previous research suggests that GPX1 could act as both a biomarker and a therapeutic target for renal cell carcinoma (RCC)." (PMID 38892221, 2024). "However, few studies have reported the expression and roles of GPX1 in renal cell carcinoma." (PMID 31844035, 2019). "However, our research also has some shortcomings, that is, the mechanism of GPX1 overexpression and molecular mechanisms of GPX1-promoting renal cell carcinoma progression remain unclear." (PMID 31844035, 2019).
cardiac hypertrophy (5 papers, 2015 to 2025). "GPX-1 deficiency has been linked to cardiac hypertrophy and dysfunction, while increased expression of HO-1 has been shown to decrease ischemic myocardial injury." (PMID 38391611, 2024). "In mice that overexpress Hsp27, there is important reductive stress characterized by an elevated GSH/GSSG ratio, increased expression and activity of GPx1, and decreased reactive oxygen species (ROS) levels, which produces cardiac hypertrophy and impaired contractile function." (PMID 40563340, 2025). "Mice lacking Gpx1 display increased cardiac hypertrophy in response to prolonged angiotensin II infusion and display increased infarct sizes following IRI8,9, suggesting that the loss of Gpx1 potentiates cardiac disease." (PMID 31857574, 2019). "GPx1 was not upregulated by these hypertrophic reagents; however, other studies suggest that GPx1 also plays an important role in mitigating the negative effects of cardiac hypertrophy and cardiac ischemia-reperfusion injury." (PMID 34579115, 2021). "Thus, in a model of Angiotensin II induced cardiac hypertrophy, absence of GPx1 enhanced left ventricular hypertrophy and decreased cardiac function." (PMID 34579115, 2021).
Cerebral ischemia (5 papers, 2012 to 2025). Restriction of arterial blood supply to the brain associated with insufficient oxygenation to support the metabolic requirements of the tissue. "It has been reported that Gpx-1 knockout mice (Gpx-1−/−) exhibit a significant reduction in cerebral blood flow that induces susceptibility to cerebral injury and cerebral ischemia." (PMID 36875474, 2023). "In our previous study we found that MMP-9 protein expression was increased in gpx-1−/− mice during cerebral ischemia-reperfusion injury." (PMID 22412999, 2012). "There is evidence of positive effects on Cu/ZnSOD, GPX1, and GPX4 activity in the cytosol of rat myocardium and brains during cardiac or cerebral ischemia." (PMID 39861168, 2025). "However, mice with ischemic brain diseases and GPX1 overexpression have significantly fewer overactivated astrocytes and microglia than corresponding mice without GPX1 overexpression." (PMID 33762907, 2021).
hyperhomocysteinemia (5 papers, 2017 to 2025). A serious metabolic condition caused by mutations in the MTHFR gene, medications, or nutritional deficiency. "Conversely, GPX1 overexpression can restore vascular function, emphasizing its crucial role in mitigating hyperhomocysteinemia-induced dysfunction." (PMID 40227195, 2025). "GPX1 is a selenoprotein negatively affected by homocysteinemia, leading to oxidative stress, reduced NO bioavailability, and ED." (PMID 40227195, 2025). "Glutathione is an important cofactor for GPx1, an intracellular antioxidant enzyme, which reduces hydrogen peroxide to water; the effect of hyperhomocysteinemia on GPx activity was determined." (PMID 38539790, 2024).
Hypertension (5 papers, 2012 to 2025). The presence of chronic increased pressure in the systemic arterial system. "In a Spanish cohort, GPX1 rs17080528 was significantly associated with CKD susceptibility (OR = 1.87, p = 0.001), and GPX4 rs713041 was associated with the hypertension incidence among CKD patients." (PMID 39857298, 2025). "It is therefore unlikely that previous associations of some of the current candidates genes (VDR, FGB, AGTR1 and GPX1) with hypertension, have influenced our results, although this cannot be completely excluded." (PMID 22879966, 2012).
inflammatory bowel disease (5 papers, 2012 to 2024). A spectrum of small and large bowel inflammatory diseases of unknown etiology. "Genetic instruments for PARK7, GPX1, and MST1 were linked to various digestive system disorders including sclerosing cholangitis and inflammatory bowel disease." (PMID 38887235, 2024). "Supporting the data presented here, GPX1 and GPX4 selenoprotein gene loci have been implicated in GWAS of inflammatory bowel disease (IBD), which is a risk factor for CRC development." (PMID 31027226, 2019). "In humans, fourteen genes affecting oxidative stress, including GPX1 and GPX4, are candidate genes for inflammatory bowel disease (IBD) and oxidative stress has been associated with IBD." (PMID 22970191, 2012).
laryngeal carcinoma (5 papers, 2013 to 2023). Carcinoma that arises from the laryngeal epithelium. "Similar protective effect of GPX1 Leu variant has been found also in the case of lung and laryngeal cancers." (PMID 29411539, 2018). "In four selenoproteins studied here we found some evidence of modest association of genetic variant in GPX1 with lung and laryngeal cancer risk." (PMID 23516596, 2013). "In analysis of four selenoprotein genes we found a modest evidence of association of genetic variant in GPX1 with the risk of lung and laryngeal cancers." (PMID 23516596, 2013). "In four selenoproteins studied here we found a modest associations of rs1050450 in GPX1 with lung and laryngeal cancer risk." (PMID 23516596, 2013). "The goal of the current study was to evaluate whether circulating zinc levels, at the time of diagnosis, and polymorphisms in SOD2, CAT and GPX1 are associated with survival among laryngeal cancer patients." (PMID 34200699, 2021). "From these results it appears the GPX1 polymorphism does not influence the effect of zinc on the survival of patients with laryngeal cancer." (PMID 34200699, 2021).
ovarian carcinoma (5 papers, 2013 to 2024). A malignant neoplasm originating from the surface ovarian epithelium. "Progression-free survival depended on the expression level of MMP12, MMP13, PYCR1 and GPx1 in patients with ovarian cancer." (PMID 38397798, 2024). "Lastly, we monitored the expression of GPX1, GPX4, and SELENOP genes in patients with ovarian cancer using the publicly available Oncomine database to elucidate the clinical significance of GPx4 in ovarian cancer." (PMID 36768241, 2023). "Oncomine revealed that the mRNA levels of GPx1 and GPx4 were strongly elevated in ovarian cancer tissues compared to those in normal ovarian tissues, whereas SELENOP levels were decreased in ovarian cancer tissues." (PMID 36768241, 2023). "In this study, we have observed the upregulation of GPX1 and 2 protein expression, increased GPX enzyme activity, and decreased intracellular ROS in response to Ets-1 overexpression in ovarian cancer cells." (PMID 24280356, 2013).
acute lymphoblastic leukemia (4 papers, 2020 to 2025). Leukemia with an acute onset, characterized by the presence of lymphoblasts in the bone marrow and the peripheral blood. "MiR-491-5p and miR-214-3p were sequestered by the lncRNA VPS9D1AS1, which elevated GPX1, promoting cell proliferation in acute lymphoblastic leukemia." (PMID 35158722, 2022). "In acute lymphoblastic leukemia (ALL), MYU promoted cell proliferation by elevating GPX1 expression by sequestering miR-491-5p and miR-214-3p." (PMID 36776216, 2023). "Additionally, the lncRNA VPS9D1-AS1 upregulates the expression of GPX1, leading to increased intracellular GSH consumption, promoting cell proliferation, and preventing cell death in the development of acute lymphoblastic leukemia (ALL)." (PMID 40403492, 2025).
asthma (4 papers, 2014 to 2025). "In particular, three ADE genes, which can be considered common susceptibility genes to asthma, such as glutathione-disulfide reductase (GSR), EPHX1, and GPX1, highlighted a relevant interaction in both variants of asthma in men and women (except for the GPX1 gene in nonallergic asthma in women)." (PMID 41154690, 2025). "However, some evidences relating to expression of SODs, CAT and GPX1 enzymes in relation to asthma or cigarette smoke were found in the literature." (PMID 30240401, 2018). "In particular, three ADE genes such as GSR, EPHX1, and GPX1 showed significant interaction in both variants of asthma in both men and women (except for the GPX1 gene in nonallergic asthma in women); therefore, they can be considered as common susceptibility genes to asthma." (PMID 24895604, 2014). "We investigated oxidative stress in severe asthma subjects by analysing urinary 8-iso-PGF2α and the mRNA-expression of the main pro-oxidant (NOX2; NOSs) and anti-oxidant (SODs; CAT; GPX1) enzymes in the airways of SAs/ex and SAn." (PMID 30240401, 2018).
brain tumors (4 papers, 2018 to 2023). "It has been proven that the binding of Pb to human GPx1 causes a decrease in the activity of this enzyme in brain tumors." (PMID 32635666, 2020). "The lack of GPx-1 exacerbated the damage caused by oxidative stress in multiple organs and tissues; therefore, it is expected that brain-tumor-induced damage promotes increased levels of gpx1 in our experimental model." (PMID 37761814, 2023). "Decreased expression of GPx1 in brain tumor cells leads to increased sensitivity to oxidative stress, while inhibition of GPx4 leads to the accumulation of lipid hydroperoxides and ferroptotic cell death." (PMID 33134322, 2020). "In the present work, the gene expression of gpx1 to gpx8 in brain tissue from animals with brain tumors induced by the transplacental administration of N-ethyl-N-nitrosourea (ENU) is analyzed in both male and female animals and compared with equivalent brain tissue from healthy animals." (PMID 37761814, 2023).
breast tumor (4 papers, 2013 to 2022). "It was first reported that breast tumours present frequent loss of heterozygosity (LOH) at the GPX1 locus associated with reduced GPx1 activity." (PMID 25988760, 2015). "On the other hand, elevated GPx1 levels in breast tumours have been associated with increased mortality risk and tumour-resistance to chemotherapy." (PMID 25988760, 2015). "They identified that SNPs in GPX1 and GPX3 and SELS genes were associated with estrogen receptor/progesterone receptor status of breast tumours." (PMID 25988760, 2015). "Moreover, alteration of anti-oxidant enzymes expression such as GPx1 has been observed in breast tumours." (PMID 25988760, 2015). "FAK was also shown to coordinate the adhesion and migration of breast tumor cells interacting with the scaffolding proteins named hematopoietic PBX-interacting protein (HPIP/PBXIP1) and glutathione peroxidase-1 (Gpx1)." (PMID 33562737, 2021). "GPX-1 and MRPL14 mRNAs are also depleted (>60%) from human breast tumor MCF-7 cells (GPX-2 is not expressed in MCF-7 cells)." (PMID 35104504, 2022).
cardiomyopathy (4 papers, 2019 to 2022). A disease of the heart muscle or myocardium proper. "Inhibition of GPx1 activity partially normalized the cardiomyopathy in Hsp27 transgenic mice, suggesting that reductive stress induced by excess GSH levels and GPx1 activity contributes to cardiac dysfunction in this model." (PMID 31218894, 2020). "Interestingly, treatment with selenium or vitamin E normalizes the antioxidant activity of myocardial GPX1 and slows the progression of cardiomyopathy." (PMID 33126466, 2020). "Furthermore, idebenone, an antioxidant drug localizing within mitochondria, that is considered as a small-molecule GPX mimetic, increases GPX1 activity and ameliorates cardiomyopathy in FRDA patients." (PMID 33126466, 2020).
cataract (4 papers, 2016 to 2023). Partial or complete opacity of the crystalline lens of one or both eyes that decreases visual acuity and eventually results in blindness. "For cataracts, GPX1 and SOD1 were expressed highly in most tissues." (PMID 37052519, 2023). "Flohé showed that the lack of GPx-1 due to alimentary selenium deprivation was inferred to induce cataracts in rats and to cause cataracts in mice by targeted gene disruption." (PMID 26875981, 2016). "A recent study showed that GPX-1 knockout lenses, but not catalase knockout lenses, showed accelerated abnormal optical aberrations and cataracts with increasing age, suggesting that GPX-1 provides primary protection for the lens against oxidative damage." (PMID 36171977, 2022). "Moreover, we found compensatory overexpression of antioxidant enzymes (SOD1, GPx‐1, and catalase) in aged lenses with cataracts in VEGF‐Ahyper mice, but not in young lenses without cataracts." (PMID 26912740, 2016).
cervical cancer (4 papers, 2020 to 2023). A primary or metastatic malignant neoplasm involving the cervix. "We detected previously unreported recurrent mutations in cervical cancer in GPX1, MSN, FAS, KRT8, and SPRED3, all genes known to modulate tumorigenic processes." (PMID 34620846, 2021). "Accordingly, knockdown of SELENBP1 in HeLa cervical cancer cells decreased ROS levels and enhanced GPx-1 expression." (PMID 38001780, 2023). "Activation of LPA3 with its highly selective agonist, OMPT, showed potent induction of mitochondrial antioxidants, glutathione peroxidase 1 (Gpx1), and superoxide dismutase type 1 and type 2 (SOD1 and SOD2) protein expression in human cervical cancer HeLa cells." (PMID 35204233, 2022). "The increased sample size enabled identification of SMGs previously unreported in cervical carcinoma including NBPF10 (8%), RANBP2 (6%), MSN (6%), KRT8 (6%), POTEC (6%), ZC3H11A (4%), BMS1 (4%), GPX1 (3%), OTOP1 (3%), DNAH12 (2%), COIL (2%), TBC1D26 (2%), SPRED3 (2%), FAM115A (2%), and ARIH1 (1%)." (PMID 34620846, 2021).